SHH (sonic hedgehog signaling molecule)
Diseases named in the same sentence as SHH in open-access papers (continued):
Sharing a sentence is not in itself a finding about the gene and the disease.
tumor (continued). "WNT and SHH subgroups showed favorable outcomes, as previously reported from IHC studies, showing low levels of tumor recurrence." (PMID 32265819, 2020). "Although the link between the SHH signaling pathway and tumorigenesis varies by cancer type, it is clear that the aberrant activation of SHH signaling leads to the growth, proliferation, and invasion of tumor cells." (PMID 32957513, 2020). "We performed targeted sequencing on 70 cases with sufficient tissues, including 15 WNT, 33 SHH, 10 Group 3, and 12 Group 4 tumours." (PMID 33172502, 2020). "There are similar observations in studies of mouse xenografts wherein the overexpression of SHH leads to higher tumor grades." (PMID 32867229, 2020). "SHH tumours originate from cerebellar granule cell progenitors (GCPs), and display excessive activation of the SHH signalling pathway." (PMID 31924815, 2020). "A unique study using arsenic trioxide, a non-specific inhibitor of Gli1/2, in a xenograft mice model demonstrated the rationale of targeting the SHH cascade in order to block ES tumor growth." (PMID 33228057, 2020). "For example, analysis of primary esophageal cancers revealed that even though the SHH transcript was localized to the tumor tissue, expression of GLI1 and PTCH1 was found in both the tumor and stroma." (PMID 32957513, 2020). "Canonical SHH signaling enhances tumor angiogenesis via mechanisms including metalloproteases, CYR61, and VEGF receptor 2 (VEGFR2), resulting in TNBC growth and metastasis." (PMID 31979397, 2020). "The SHh signaling pathway is a major regulator of tumorigenesis, tumor progression and therapeutic response." (PMID 32430068, 2020). "This article reviews the recent studies of the role of SHH in organogenesis, tumors, and tumor microenvironments." (PMID 31979397, 2020). "Early abrogation of the pathway by an anti-SHH/IHH antibody 5E1 led to significantly worse survival with increased tumor and metastatic burden." (PMID 32108165, 2020). "The data here suggest that IHH is sufficient to suppress tumor initiation and growth and that SHH is dispensable for LAD tumorigenesis." (PMID 32108165, 2020). "SHH ligands exhibited by pancreatic cancers promote tumor growth indirectly via SHH signaling activation in the surrounding stroma." (PMID 31979397, 2020). "A surprising result of our studies was the central role of IHH, instead of SHH, to suppress tumor growth." (PMID 32108165, 2020). "For OS, the consequences of an alteration of the SHH pathway in tumor development have been evaluated in several cell models and in preclinical animal models." (PMID 33228057, 2020). "This paracrine activation of SHH signaling in the tumor microenvironment affords an environment favorable for the proliferation, metastasis, and drug resistance of cancer cells." (PMID 31979397, 2020). "(H) Expression of SHH or BMPR1A in tumor xenografts from mice injected with J82 carrying shRNA targeting SHH or BMPR1A, respectively." (PMID 31036156, 2019). "After 4 weeks, the cells were treated with recombinant sHH, or Cyc, then, the average tumour mass of different cell groups was measured." (PMID 30761741, 2019). "To determine the effect of the tumor suppressor IL-24 on the expression of SHH signaling components, we used the H1299 cell line (labeled ‘H1299-IL24’), which was stably transfected with doxycycline-inducible plasmid vector (pTET-IL-24)." (PMID 31783569, 2019). "The rapid depletion of the non-glial Hes1+ populations after vismodegib treatment would also support a direct relationship between SMOM2-mediated SHH hyperactivation and Hes1 expression in tumor cells." (PMID 31863004, 2019). "Together, these results suggest that the inhibition of the SHH pathway leads to an increase in clonogenic tumour cells, with increased proliferative capacity, which promotes the development of premature tumour lesions." (PMID 30645190, 2019).
tumor (continued). "SHH/GLI pathway is known to promote self-renewal of cancer stem cells (CSCs) by transcriptionally regulating expression of various genes including tumor metastasis." (PMID 30899425, 2019). "We were the first to show SHH gene expression in human MPM tumor tissues along with increased expression levels of HHIP and GLI1." (PMID 31788004, 2019). "The SHH signaling pathway is not only involved in regulation of tumor angiogenesis but is also important for tumor migration and invasion." (PMID 31744214, 2019). "Some studies have reported the details of the contribution of SHH to tumor angiogenesis and also reported the contribution of SHH to angiogenesis of OSCC." (PMID 31744214, 2019). "Aberrant activation of Sonic Hedgehog (SHH) pathway seems to play a key role in the genetic background of the tumor development." (PMID 31342143, 2019). "To determine the effect of EIF5A and sHH signalling on PC tumour growth in vivo, we assessed orthotopic tumour formation of Panc‐1 cells with Si‐EIF5A." (PMID 30761741, 2019). "Here, we show that this activation is ligand dependent and induced by the expression of SHH protein in a small proportion of tumour cells." (PMID 30645190, 2019). "In vitro experiments and transplant models in mice indicate a correlation between local tumor invasion, visceral and osteolytic metastasis and constitutive SHH expression in TNBC." (PMID 31027259, 2019). "It has already been proven that dysfunctions of the SHH signaling cascade lead to the development of various diseases or neoplasia." (PMID 30769952, 2019). "Strong association was observed between expression of SHH and GLI1 in the tumor samples (r = 0.42, p < 0.0001)." (PMID 31036836, 2019). "Initial IDHWT tumours also showed predicted pathogenic variation in NOTCH (11%) and SHH (13%) pathways including PTCH1 (PATCHED-1) and SMO (Smoothened)." (PMID 32082376, 2019). "Together, these results suggest that chemical SHH pathway inhibition using vismodegib in Hesx1Cre/+;Ctnnb1lox(ex3)/+ mice results in the formation of aggressive tumours." (PMID 30645190, 2019). "The molecular diagnosis of MB has made it easier to differentiate tumor subgroups, with very reliable diagnostic markers available for WNT and SHH MBs, but group 3 and group 4 tumors are more difficult to define." (PMID 31763623, 2019). "Reinforcing the mouse data, SHH pathway inhibition in human ACP leads to a significant increase in tumour cell proliferation both ex vivo, in explant cultures, and in vivo, in a patient-derived xenograft model." (PMID 30645190, 2019). "SHH overexpression promotes tumor growth and metastasis, and higher levels of SHH are associated with poor survival and poor prognosis." (PMID 31744214, 2019). "While vismodegib produced an overall increase in differentiation, different populations of tumor cells demonstrated different responses to disruption of the SHH pathway." (PMID 31863004, 2019). "Compared with patients with low SHH expression level in tumor tissues, patients with high SHH expression level had significantly lower overall survival rate." (PMID 31898580, 2019). "Collectively, these results demonstrated that EIF5A and sHH signalling pathway was sufficient and necessary for tumour growth in PC." (PMID 30761741, 2019). "Many tumor blood vessels, which expressed both SHH and PTCH, were observed in the cancer stroma, and the accumulation of these blood vessels was adjacent to the site where SHH was strongly expressed in the cancer parenchyma." (PMID 31744214, 2019). "In a TNBC cohort, increased SHH and SMO expression was associated with high histological grades, and SMO and GLI1 correlated with high tumor stages." (PMID 31027259, 2019). "This upregulation of SHH in the tumor cells in turn lead to higher CXCL12 expression in stromal cells, conferring a bidirectional tumor-stromal feedback loop for tumorigenesis." (PMID 31561620, 2019).
tumor (continued). "In the tumor, the Hh pathway ligands, SHH and IHH, had undetectable expression consistent with ligand-independent Hh pathway activation following PTCH1 inactivation." (PMID 31362756, 2019). "In summary, using a clinically approved and widely employed SMO inhibitor in both the Hesx1Cre/+;Ctnnb1loxex3/+ mice and a human xenograft model, our research demonstrates that the inhibition of the SHH pathway has a tumour-promoting effect." (PMID 30645190, 2019). "Baseline transcription of SHH was higher in untreated EAC tumours compared to normal esophagus, mirroring previously published findings." (PMID 29715275, 2018). "As a result, the crosstalk of SHH pathway with other pathways should be taken into account in the design and development of novel drugs since tumour escape has been reported." (PMID 30096798, 2018). "Over expression of SHH, DHH and GLI1 were associated with cell grades in Finak dataset and also related with poorly differentiated tumours." (PMID 29329585, 2018). "In our previous studies, we found that SHH signaling pathway contribute to mediate the tumor-like behavior of FLSs depending on SMO." (PMID 30568656, 2018). "As a mediator of tumorigenesis, paracrine SHH signaling plays an important role in the communication between tumor and activated fibroblasts." (PMID 29042665, 2017). "SHH-dependent MBs arise from granule cell precursors (GCPs), are fatal in 40–70% of cases and radioresistance strongly contributes to poor prognosis and tumor recurrence." (PMID 29079783, 2017). "While non- aggressive human BCC subtypes display high NEO1 expression, aggressive human BCC subtypes present with lower levels of NEO1, similar to GLI1, suggesting a possible role of SHH/GLI/NEO1 signaling in tumor aggressiveness." (PMID 29137400, 2017). "Using cell-based models of sonic hedgehog (SHH) and group 3 (G3) MB, we quantified tumour growth and infiltration and determined the morphological characteristics of the infiltrating cells." (PMID 28706234, 2017). "Our data are consistent with previous findings that SHH is overexpressed in pancreatic tumour cells and that tumour cell-derived SHH activates the Hh signalling pathway in pancreatic stellate cells instead of in tumour cells." (PMID 28978035, 2017). "Sonic hedgehog (SHh) signaling was recognized as one of the key regulators of tumor epithelia–stromal interaction in PDAC." (PMID 28753978, 2017). "Grp4 was most common (n = 62; 58%), with approximately equivalent numbers of WNT (18/170; 16%), SHH (17/107; 16%) and Grp3 (10/107; 9%) tumours observed." (PMID 29044166, 2017). "Tumor cells express SHH, which can promote cell proliferation and epithelial-to-mesenchymal transition." (PMID 27039174, 2016). "From an analysis of surgically resected lower gingival squamous cell carcinoma mandible samples, we found that SHH was highly expressed in tumor cells that had invaded the bone matrix." (PMID 27007126, 2016). "More importantly, the SHH pathway inhibitor Vismodegib has been used as an adjunctive therapy in patients with NBCCS to reduce tumor size and reduce the margins needed for surgical resection." (PMID 27066764, 2016). "SHH knockdown in SAS cells tumor engrafts attenuated the recruitment of new vasculature to the tumor, suggesting the involvement of SHH in tumor-associated angiogenesis." (PMID 27007126, 2016). "We found that compared with tumor tissues, 9 patients (9/30) have low SHH expression in tumor tissues, and 21 patients (21/30) have high SHH expression in tumor tissues." (PMID 27039174, 2016). "Collectively, the SHH signalling pathway can regulate the tumour cell cycle and apoptosis at different molecular levels." (PMID 27601167, 2016). "In agreement, cell-specific analysis of PDA proliferation in homo and heterocellular cultures revealed increased tumor cell proliferation under heterocellular conditions (via SHH, IGF1R/AXL, and AKT activity)." (PMID 27087446, 2016).
tumor (continued). "In the mouse model, SHH inhibitors significantly reduced tumor incidence and multiplicity, decreased the expression of IL-6, TNF-α, COX-2, STAT3, and NF-κB, and significantly induced apoptosis." (PMID 26716648, 2016). "In MM-derived cells, the tumor cells secrete SHH; autocrine SHH signaling induces cell proliferation, chemotherapy resistance, and protection against apoptosis by upregulating BCL2." (PMID 26988232, 2016). "SHH protein expression in GC tissue and adjacent non-tumor tissue was analyzed using western blot in a cohort of 30 patients." (PMID 27039174, 2016). "In some tumor types, SHH-driven tumorigenesis is sensitive to the disruption of KIF3A, a subunit of the kinesin-2 motor whose anterograde function is required for ciliogenesis." (PMID 26760767, 2016). "Tumor conditioned media (TCM) lead to a similar pattern of HH target gene induction as seen with recombinant SHH." (PMID 26755648, 2016). "SHH was highly expressed in tumor cells that had invaded the bone matrix, and weakly expressed in osteoclasts." (PMID 27007126, 2016). "SHH expression at the mRNA level in GC tissue and adjacent non-tumor tissue was analyzed using qRT-PCR in a cohort of ten patients." (PMID 27039174, 2016). "The only MYCN amplification was found in a case with a 9q deletion encompassing the PTCH1 locus, which strongly suggests this tumor belongs to the SHH subgroup." (PMID 26857864, 2016). "The reactivation of SHH signaling in response to chemotherapy has been shown to play a major role in tumor refractoriness." (PMID 25595896, 2015). "In another mouse model of MB, in which PTCH1 is inactivated, bortezomib had anti-tumor activity, down-regulated the SHH pathway and restored PTCH1 levels." (PMID 26475605, 2015). "We here show that HIF-1α regulates the SHH pathway in NB and further influences the growth and progression of the tumor." (PMID 25811359, 2015). "We detected expression of HH effectors, GLI transcription factors, and PTCH receptor in all cell lines, while moderate SHH expression was detected only in HeLa cells, suggesting constitutively active SHH signaling in this tumor-derived cell line." (PMID 26588701, 2015). "OLFM4 was significantly downregulated in metastatic tumor tissue when compared with normal prostate tissue, whereas SHH was significantly upregulated in metastatic tumor tissue when compared with normal prostate tissue (upper row)." (PMID 26581960, 2015). "This study investigated the role of sonic hedgehog (SHH) and Wnt signaling pathways in tumor repopulation after radiotherapy in an in vitro repopulation model." (PMID 25713298, 2015). "Notch1 and SHH play important and complex roles in the proliferation and differentiation processes of tumor cells." (PMID 26563263, 2015). "Downstream Gαs signaling mediated through cAMP levels suppresses SHH signaling, and mice harboring the GNAS mutation demonstrate decreased tumor proliferation when cAMP levels are elevated." (PMID 26512695, 2015). "Positive expression of HIF-1α was found in 57.7% of all the tumor samples from all clinical stages, and the degree of positive staining for SHH, PTCH1 and GLI1 was 64.8%, 46.5%, and 54.9%, respectively." (PMID 25811359, 2015). "The present study revealed a significant increase in SFRP1, SHH and Gli1 expression in irradiated tumor cells." (PMID 25713298, 2015). "The protein level of SHH (ligand) and Gli1 (a transcription factor that can activate the transcription of SHH target genes) were increased in irradiated tumor cells with a peak at 6 Gy." (PMID 25713298, 2015). "In mice injected with HIF-1α-overexpressing cells, but given GANT61, the tumor volume was remarkably smaller (P < 0.0001), suggesting that the positive effect of HIF-1α on tumor growth was antagonized via inhibiting the SHH pathway." (PMID 25811359, 2015).
tumor (continued). "For example, in one study of xenografted tumors, GLI1 mRNA localized to the stromal compartment while SHH localized to the prostatic epithelium, indicating active paracrine Hh signaling from the tumor in the surrounding stroma." (PMID 26426053, 2015). "Our results highlight the interaction between Wnt and SHH signaling pathways in dying tumor cells and suggest that downregulation of Wnt signaling after SHH activation is negatively associated with tumor repopulation." (PMID 25713298, 2015). "In a multivariate model, increased SHH expression was an independent prognostic factor for biochemical recurrence beyond clinical factors that included Gleason score, stage, tumor volume, and pretreatment PSA." (PMID 26426053, 2015). "Ectopic expression of SHH in murine basal keratinocytes has been suggested to result in increased proliferation and tumor development." (PMID 26694869, 2015). "Targeting the tumor stroma using a sonic hedgehog (SHH) inhibitor in combination with gemcitabine in the KPC mouse model (a transgenic expression model of PDAC) resulted in elevated gemcitabine levels in the tumors and increased cancer cell destruction." (PMID 25337831, 2014). "Since it has been demonstrated that the inhibition of SHh-signaling can inhibit BCC tumor growth, diverse small molecule inhibitors of specific SHh signals are under study for the BCC targeted therapy." (PMID 25101298, 2014). "Recent studies have implicated inherited or sporadic alterations in SHH signaling pathway genes in a number of developmental defects and aberrant activation of the SHH signaling pathway can result in tumor formation." (PMID 23835807, 2013). "In this study, we examined the roles of SHH signaling pathway in dying cell stimulated tumor cell growth." (PMID 23762282, 2013). "To further confirm the roles of SHH signaling on dying tumor cell stimulated living tumor cell growth, we tested another Gli1 antagonist (Gant61)." (PMID 23762282, 2013). "In this study, we further explored the concept of dying cells signaling surviving tumor cells to grow by investigating the role of the SHH signal pathway during this process." (PMID 23762282, 2013). "The recent development of small molecule inhibitors of the SHH pathway holds promise for the treatment of these tumor subgroups." (PMID 24252460, 2013). "A broad viewing of the GPCR expression patterns heat map shows that the Non- WNT/SHH tumors reside in two large tumor groups, interspersed with tumors for which immunohistochemistry -based subgroup categorization was not possible." (PMID 24252460, 2013). "Essentially, the discovery of our proposed SHH signaling induced tumor cell repopulation has relevant clinical applications for future cancer treatment with radiation." (PMID 23762282, 2013). "We further confirmed the role of SHH signaling in dying tumor cell stimulated living tumor cell growth by using shRNA to knockdown Gli1 expression in feeder cells." (PMID 23762282, 2013). "The idea of the SHH pathway contributing to tumor cell growth after radiation therapy is consistent with our current understanding of this pathway in tumor biology." (PMID 23762282, 2013). "The SHH-antagonist HH-Antag induces bone defects when administered to young tumor prone mice and a patient treated with the SHH-antagonist GDC-0449 became resistant to the drug due to mutations in the targeted receptor Smoothened (SMO)." (PMID 23527084, 2013). "The in vitro tumor cell death effect and the in vivo antitumor effect of SHH interference on SHH-expressing tumor cells support the view that the SHH–CDON interaction is a potential target for drug development." (PMID 23940460, 2013). "The general view is that this autocrine or paracrine SHH expression is a mechanism that constitutively activates Ptc-Smo signaling either in tumor cells or more generally in stromal cells." (PMID 23940460, 2013).